ARL4C (ARF like GTPase 4C)
Description:
Small GTP-binding protein which cycles between an inactive GDP-bound and an active GTP-bound form, and the rate of cycling is regulated by guanine nucleotide exchange factors (GEF) and GTPase-activating proteins (GAP). GTP-binding protein that does not act as an allosteric activator of the cholera toxin catalytic subunit. May be involved in transport between a perinuclear compartment and the plasma membrane, apparently linked to the ABCA1-mediated cholesterol secretion pathway. Recruits CYTH1, CYTH2, CYTH3 and CYTH4 to the plasma membrane in the GDP-bound form. Regulates the microtubule-dependent intracellular vesicular transport from early endosome to recycling endosome process.
Synonyms: ARL7; LAK
Tractability: Antibody: its Gene Ontology location is reachable by antibodies, with high confidence; UniProt places it where antibodies can reach, with medium confidence; the Human Protein Atlas places it where antibodies can reach. PROTAC: ubiquitination databases record sites on it; its protein half-life has been measured.
Gene: Protein-coding gene on chromosome 2 (234,493,041 to 234,497,081, reverse strand). Ensembl gene ENSG00000188042.
Subcellular location: Cell projection, filopodium; Cell membrane; Cytoplasm
Subcellular location (Human Protein Atlas): Plasma membrane; Cytosol
Pathways (Reactome):
Signal Transduction: NR1H3 & NR1H2 regulate gene expression linked to cholesterol transport and efflux
Gene Ontology:
Molecular function: alpha-tubulin binding; protein binding; GTP binding; GTPase activity
Biological process: endocytic recycling; intracellular protein transport
Cellular component: cytoplasm; cytosol; mitochondrion; plasma membrane; nucleus; filopodium
Genetic constraint (gnomAD): Loss-of-function variants: 6 observed, 14.88 expected, observed/expected ratio (o/e) 0.4, 90% interval 0.22 to 0.8. The upper end of that interval is the gene's LOEUF score, 0.8, which puts it in group 3 of 6, group 1 being the genes least tolerant of losing a copy. Missense variants: 148 observed, 279.3 expected, observed/expected ratio (o/e) 0.53, 90% interval 0.46 to 0.61. Synonymous variants: 119 observed, 121.41 expected, observed/expected ratio (o/e) 0.98, 90% interval 0.84 to 1.14.
Homologues: Orthologues: chimpanzee ARL4C (100% identical), macaque ARL4C (99% identical), pig ARL4C (97% identical), dog ARL4C (96% identical), mouse Arl4c (96% identical), rabbit ARL4C (96% identical), rat Arl4c (96% identical), zebrafish arl4ca (91% identical), tropical clawed frog arl4c (88% identical). Paralogues in human: ARL4A (67% identical), ARL4D (57% identical), ARF3 (44% identical), ARF1 (44% identical), ARF5 (43% identical), ARF4 (42% identical), ARF6 (39% identical), TRIM23 (38% identical), ARL1 (38% identical), ARL11 (38% identical), ARL14 (37% identical), ARL3 (36% identical), and 18 more.
Diseases named in the same sentence as ARL4C in open-access papers:
ARL4C is named in the same sentence as 75 diseases in open-access papers, as found by Europe PMC text mining. Sharing a sentence is not in itself a finding about the gene and the disease. The quoted sentences say what the papers report.
colorectal cancer (11 papers, 2020 to 2026). A primary or metastatic malignant neoplasm that affects the colon or rectum. "ARL4C is associated with initiation and progression of leukomyosarcoma, glioblastoma, lung adenocarcinoma and lung squamous cell carcinoma, ameloblastoma, colorectal cancer, liver cancer, gastric cancer, and renal cell carcinoma." (PMID 39767779, 2024). "Recent studies demonstrated that ARL4C promotes the progression of lung cancers, colorectal cancers, and gastric cancers." (PMID 36778920, 2023). "It has been found that ARL4C is overexpressed in colorectal cancers and plays a pivotal role in the progression of CRC." (PMID 35047006, 2021). "A novel targeted nucleic acid drug targeting ARL4C inhibits the expression of ARL4C in colorectal cancer cells, and ultimately reduces the proliferation and migration of cancer cells." (PMID 33959617, 2021). "The prognostic value of ARL4C in colorectal cancer was also evaluated and the same authors concluded that patients with higher expression of ARL4C have lower survival on average." (PMID 32426352, 2020). "This suggests that the molecular mechanisms involved in the role of ARL4C in hepatocellular carcinoma are different from those in lung and colorectal cancers." (PMID 32426352, 2020). "In addition, ARL4C is a promising biomarker for the diagnosis of renal cancer, gastric cancer, colorectal cancer, and lung adenocarcinoma in preclinical and clinical trials." (PMID 40176913, 2025). "The ARL4C gene is highly expressed in colorectal cancer (CRC)." (PMID 37237373, 2023). "It has been found that overexpression of ARL4C might contribute to the tumorigenesis and lead to worse prognosis in colorectal cancer, which supported the result of our study." (PMID 35237578, 2022). "Furthermore, analysis of ARL4C expression in colorectal cancer samples revealed that this ARL is more expressed in tumor samples, comparing with adjacent normal tissue." (PMID 32426352, 2020). "Although some prognostic involvement of ARL4C expression in colorectal carcinoma has been suggested, our analysis reinforces the possibility that ARL4C expression worsens the prognosis in CRC." (PMID 37237373, 2023). "Downregulation of ARL4C with siRNA and anti-sense oligonucleotide (ASO), such as ASO-1316, is developing in preclinical research for the treatment of lung adenocarcinoma, liver cancer, and colorectal cancer." (PMID 40176913, 2025). "Downregulation of ARL4C with siRNA and antisense oligonucleotides (ASOs), such as ASO-1316, is investigated in preclinical research for the treatment of lung adenocarcinoma, liver cancer, and colorectal cancer." (PMID 40176913, 2025). "It has been reported that down‐regulation of ARL4C might prevent nuclear localization of YAP/TAZ in lung cancer cells and colorectal cancer cells." (PMID 33724652, 2021).
lung carcinoma (11 papers, 2016 to 2024). "As a tumor-related gene, ARL4C is associated with lung cancer, colorectal cancer, gastric cancer, testicular cancer, melanoma, primary human glioblastoma, and ovarian cancer, among others." (PMID 35774359, 2022). "In lung cancer research, the ubiquitination regulation mechanism of Arl4c is studied, and potential chemotherapeutic drugs targeting Arl4c are explored." (PMID 39268462, 2024). "The hypomethylation at the cg24441922 site in particular has been found to contribute to the dysregulation of ARL4C in lung cancer, and we found the same result for BC." (PMID 36367890, 2022). "Fuji's study shows that the hypomethylation in the 3’‐UTR induces the overexpression of ARL4C in lung cancer, which contributes to the malignant phenotypes of cancer cells." (PMID 33724652, 2021). "In colon and lung cancer cells, ARL4C promotes cell proliferation through ARF6, RAC, RHO, and YAP/TAZ." (PMID 34590580, 2021). "The regulation of the drug resistance of lung cancer cells by ARL4C was through activating the β-catenin/JAK2/STAT5A signaling pathway." (PMID 33194732, 2020). "ASOs targeting ARL4C (ASO-1316) showed decreased RAS-related substrate activity, inhibited cell proliferation and migration, and suppressed nuclear import of Yes-associated protein-1 (YAP-1) in lung cancer cell lines bearing KRAS and EGFR mutations." (PMID 33740988, 2021). "ARL4C promotes cell proliferation and is a potential therapeutic target for lung cancer." (PMID 33740988, 2021). "ARL4C expression promotes the progression of colorectal and lung cancers in vitro and in vivo." (PMID 33724652, 2021). "Whether ARL4C is expressed in human cancers other than adenocarcinomas, such as colon and lung cancers, was investigated in SCCs." (PMID 27835592, 2016). "Consistent with the previous results with IEC6 rat intestinal epithelial cells and colorectal and lung cancer cells, the MEK inhibitors PD184161 and U0126 and siRNAs for β-catenin and KRAS decreased ARL4C expression in S2-CP8 and PANC-1 cells." (PMID 34590580, 2021). "ARL4C ASO-1316 has been shown to inhibit growth of xenograft tumors induced by colon and lung cancer cells." (PMID 34590580, 2021). "ADP-ribosylation factor like 4C (ARL4C), a member of small GTP-binding protein family, is frequently overexpressed in adenomatous hyperplasic lesions (precursors to adenocarcinoma) and lung cancer." (PMID 33740988, 2021). "Correlation of ARL4C expression with clinical features of colorectal or lung cancer indicates that ARL4C expression does not change with tumor T grade or lymph node metastasis grade, indicating that it is involved in the occurrence rather than the development of such cancers." (PMID 35774359, 2022). "Another study found that the AKT pathway is an important regulatory pathway for ARL4C expression in lung cancer cells, and the authors showed that the chemotherapeutic drug hydroxycamptothecin (HCPT0) could be used to treat the lung adenocarcinoma by targeting the expression of ARL4C." (PMID 35774359, 2022). "However, a previous study has shown that overexpression of ARL4C could promote cancer cell proliferation in 3D and in vivo experiments, while the 2D assays could not yield the similar results in colon cancer and lung cancer." (PMID 33724652, 2021).
pancreatic cancer (9 papers, 2020 to 2025). "Moreover, increased expression of Arl4c has been associated with the activation of pancreatic stellate cells (PSCs) and increased drug resistance in pancreatic cancer." (PMID 38404591, 2024). "ARL4C can be used as a prognostic biomarker for the survival of patients with pancreatic cancer treated with gemcitabine and has been patented by Acobiom (patent number: WO2016027029A2)." (PMID 40176913, 2025). "In pancreatic cancer, ARL4C participates in microenvironment remodeling and promotes tumor growth and drug resistance too." (PMID 35607443, 2022). "TCGA dataset revealed that expression of ARL4C mRNA in pancreatic cancer patients is positively correlated with that of IQGAP1 mRNA." (PMID 34590580, 2021). "Taken together, these results suggest that ARL4C ASO inhibits the invasion of tumor cells into lymphatic vessels in vivo, and the gene profiles of tumors treated with ARL4C ASO in vivo support the putative functions of ARL4C in pancreatic cancer invasion." (PMID 34590580, 2021). "In the present study, we found that ARL4C is frequently overexpressed in pancreatic cancer patients and showed that its localization to invasive pseudopods is required for cancer cell invasion." (PMID 34590580, 2021). "In this study, we found that the ARL4C–IQGAP1–MMP14 signaling axis is involved in pancreatic cancer invasion." (PMID 34590580, 2021). "PSCs in pancreatic cancer specimens with high Arl4c expression have a higher αSMA expression, whereas these in pancreatic cancer specimens with low Arl4c expression often lose αSMA expression." (PMID 34849465, 2021). "Statistical analysis revealed that expression levels of Arl4c were significantly correlated with αSMA expression levels (r = 0.6664, P < 0.001), suggesting Arl4c correlates with tumor fibrosis in pancreatic cancer." (PMID 34849465, 2021). "TCGA dataset showed that expression of MMP14 mRNA in pancreatic cancer patients is positively correlated with that of both ARL4C and IQGAP1 mRNA." (PMID 34590580, 2021). "Taken together, these results indicate that high expression of ARL4C is correlated with the aggressiveness and poor prognosis of pancreatic cancer." (PMID 34590580, 2021). "The TGFβ1 neutralizing antibody abolished the effect of Arl4c on promoting the stemness and drug resistance of pancreatic cancer cells." (PMID 34849465, 2021). "To assess the potential clinical relevance of our findings, we detected the expressions of Arl4c and αSMA in 52 pancreatic cancer specimens." (PMID 34849465, 2021). "Pancreatic cancer tissues were stained with anti-ARL4C, anti-IQGAP1, and anti-MMP14 antibodies in the serial section." (PMID 34590580, 2021). "Invasive pseudopods that we defined in these pancreatic cancer cells highly expressing ARL4C consisted of similar molecules, including cortactin, ARPC2, IQGAP1, and MMP14, which are involved in invadopodia functions." (PMID 34590580, 2021). "Taken together, these results suggest that ARL4C is expressed in pancreatic cancer cells through activated RAS–MAP kinase and Wnt–β-catenin pathways." (PMID 34590580, 2021). "In cultured pancreatic cancer cell lines, ARL4C was highly expressed in PANC-1 and S2-CP8 cells and it was barely detected in BxPC-3 cells." (PMID 34590580, 2021). "Taken together, these results support the idea that the ARL4C–IQGAP1–MMP14 signaling axis participates in pancreatic cancer cell invasion." (PMID 34590580, 2021). "In this report, we aimed to explore the role of Arl4c in pancreatic cancer growth and drug resistance, as well as PSC activation, further determine its effect on tumor-stromal interactions, and reveal the underlying mechanism." (PMID 34849465, 2021). "In this study, we showed Arl4c is required for cell growth and drug resistance of pancreatic cancer." (PMID 34849465, 2021). "(C) Sections from the pancreatic tumors from control ASO- or ARL4C ASO-1316-treated tumor-bearing mice were stained with anti-ARL4C antibody and hematoxylin." (PMID 34590580, 2021).
pancreatic cancer (continued). "In primary pancreatic tumors, ARL4C ASO-1316 reduced ARL4C expression at protein and mRNA levels and decreased the localization of IQGAP1 to the cell surface area." (PMID 34590580, 2021). "Our clinical and mechanistic findings establish that the Arl4c-Yap-CTGF axis is critical for pancreatic cancer progression and that treatments targeting this axis might be a potential therapeutic strategy for pancreatic cancer." (PMID 34849465, 2021). "Moreover, subcutaneously injected antisense oligonucleotide against ARL4C into tumor-bearing mice suppressed metastasis of pancreatic cancer." (PMID 34590580, 2021). "Strategies targeting Arl4c may be a therapeutic choice for patients with pancreatic cancer, especially for gemcitabine-resistant patients." (PMID 34849465, 2021). "The inhibition of ARL4C expression by ARL4C ASO could directly inhibit invasive ability of pancreatic cancer cells and may indirectly affect the genes involved in invasion perhaps through the interaction between tumors and surrounding tissues." (PMID 34590580, 2021). "Based on these results, Arl4c promotes cell proliferation and drug resistance in pancreatic cancer." (PMID 34849465, 2021). "We detected the expression of several markers of cell stemness, such as CD44, CD133, OCT4, Nanog, and KLF4, to test whether the effect of Arl4c on promoting drug resistance in pancreatic cancer is attributed to its role in regulating cell stemness." (PMID 34849465, 2021). "In conclusion, this study clarified that invasion of pancreatic cancer cells is promoted by ARL4C, of which expression is induced by KRAS and Wnt signaling, and that association of ARL4C with IQGAP1 and MMP14 at the tips of invasive pseudopods are essential for the invasive ability." (PMID 34590580, 2021). "ARL4C expression is especially involved in the invasion of pancreatic cancer cells." (PMID 34590580, 2021). "Because PI3 kinase is one of the direct effector proteins of RAS, RAS-dependent PI3 kinase activation and ARL4C expression could co-operatively function to promote pancreatic cancer invasion." (PMID 34590580, 2021). "Taken together, these results suggest that Arl4c is essential for pancreatic cancer progression and may be an effective therapeutic choice." (PMID 34849465, 2021). "Since the clinicopathological analysis of human pancreatic cancer specimens indicates that ARL4C expression may be correlated with invasive ability, migratory and invasive abilities of S2-CP8 and PANC-1 cells were studied in Boyden chamber assays." (PMID 34590580, 2021). "BTG2 was poorly expressed in pancreatic cancer, while ARL4C was highly expressed." (PMID 33425718, 2020). "Inhibiting ARL4C (siRNA, antisense oligonucleotide, ribozyme, and siRNA expression vector) for the treatment of cancer (such as liver cancer, colon cancer, lung cancer, tongue cancer, and pancreatic cancer) was investigated by Osaka University NUC (patent number: JP06436477B2 and WO2020050307A1)." (PMID 40176913, 2025). "Similarly, AHNAK2, ARL4C, ASAP2 were all highly expressed in pancreatic cancers, correlated with KRAS G12D mutation and could predict survival in pancreatic cancers." (PMID 35785187, 2022). "Meanwhile, components of invadopodia, such as cortactin and ARPC2, were localized at the tips of protrusions defined above, with ARL4C, suggesting that the protrusions might contribute to invasive phenotypes of pancreatic cancer cells and ARL4C functions there." (PMID 34590580, 2021). "We further explored whether Arl4c affected the drug resistance of pancreatic cancer cells." (PMID 34849465, 2021). "Whether ARL4C is expressed in pancreatic cancer patients was examined using immunohistochemistry." (PMID 34590580, 2021). "AHNAK2, ARL4C, ASAP2, SEMA3C were identified as being highly expressed in both KRAS G12D cell lines and pancreatic cancer patients." (PMID 35785187, 2022).
pancreatic cancer (continued). "Protease activity was decreased when ARL4C was depleted, suggesting that ARL4C is involved in degradation of the ECM through its localization to the tips of invasive pseudopods and plays an important role in the invasion of pancreatic cancer cells." (PMID 34590580, 2021). "(L) Scatter plot showing the correlation between the mRNA expression levels of ARL4C (X-axis) and IQGAP1 (Y-axis) in pancreatic cancer patients obtained from TCGA datasets using the R2: Genomics Analysis and Visualization Platform." (PMID 34590580, 2021). "Because ARL4C expression is induced by Wnt and EGF signaling, it is reasonable that ARL4C would be expressed in a β-catenin- and RAS-dependent manner in pancreatic cancer cells." (PMID 34590580, 2021). "These prompted us to study the involvement of ARL4C, as a KRAS downstream molecule, in aggressiveness of pancreatic cancer, and IQ-domain GTPase-activation protein 1 (IQGAP1) was identified as a binding protein of ARL4C." (PMID 34590580, 2021). "Thus, ARL4C could be involved in migration and invasion of pancreatic cancer cells." (PMID 34590580, 2021). "ARL4C was identified as RAF1-MEK/ERK pathway-dependent gene in ameloblastoma cell proliferation and osteoclast formation and as down localization of KRAS in pancreatic cancer." (PMID 35785187, 2022). "In pancreatic cancer cells, we did not observe any obvious changes in either mRNA or protein levels of these markers when Arl4c was knocked down or upregulated compared with the control group (data not shown)." (PMID 34849465, 2021). "Thus, simultaneous expression of ARL4C and IQGAP1 would be correlated with aggressiveness of pancreatic cancer." (PMID 34590580, 2021). "Although ARL4C induces the nuclear import of YAP/TAZ in HCT116 cells, ARL4C knockdown did not inhibit it in pancreatic cancer cells." (PMID 34590580, 2021). "However, ARL4C ASO-1316 had little effect on sphere formation of pancreatic cancer cell and did not induce cell death, which is assessed by propidium iodide (PI) staining." (PMID 34590580, 2021). "In this study, we identified a critical role for Arl4c in pancreatic fibrosis and drug resistance via Yap 1-dependent CTGF paracrine signaling and subsequent increases in the autophagy level and activation of PSCs, which led to pancreatic cancer cell self-renewal and stemness." (PMID 34849465, 2021). "Moreover, we detected ARL4C and BTG2 expression in pancreatic cancer tumor tissues and adjacent normal tissues and found that BTG2 was downregulated and ARL4C was upregulated in pancreatic cancer tumor tissues compared with adjacent normal tissues." (PMID 33425718, 2020).